INS (insulin)
Diseases named in the same sentence as INS in open-access papers (continued):
Sharing a sentence is not in itself a finding about the gene and the disease.
type 2 diabetes (continued). "The second Phase II study compared BIF with degludec in 278 insulin-naive participants with type 2 diabetes being treated with metformin with or without a DPP4i and/or sodium–glucose cotransporter 2 inhibitor (SGLT2i), with a fasting glucose target of 4.4–5.6 mmol/l." (PMID 38679644, 2024). "However, this hypothesis needs well-conducted large cohort and interventional studies to evaluate the morbidity of type 2 diabetes and the effect of CPAP treatment on INS sensitivity and glucose metabolism in women affected by both PCOS and OSAHS." (PMID 39247914, 2024). "Moreover, a recent study found Cinnamon reduces FBS, HOMA-IR, and HbA1c in type 2 diabetes patients, though it does not significantly alter serum insulin levels." (PMID 39593185, 2024). "As a proof-of-concept, first-in-patient trial in people with type 2 diabetes, the inclusion/exclusion criteria were more restrictive and therefore the results may not be generalisable to the entire insulin-naive type 2 diabetes population." (PMID 38095657, 2024). "Additionally, our findings showed that DSEP is cost-effective for a subgroup of patients with type 2 diabetes who have HbA1c levels greater than 7% and are not treated with insulin." (PMID 39639901, 2024). "Butyrate, a short-chain fatty acid produced by microbiota, might improve type 2 diabetes features by increasing glucagon-like peptide-1 (GLP-1), an incretin hormone that participates in glucose homeostasis recovering fasting glycemia, insulin resistance, and inflammation." (PMID 38750102, 2024). "All participants were taking insulin, a medication usually used in more advanced type 2 diabetes, and the results may not be generalisable to other patient populations." (PMID 38584180, 2024). "Type II diabetes was induced via the injection of NA/STZ in male rats fed with a high-fat diet for 8 weeks, resulting in a significant elevation of blood glucose levels by destroying the β-cells of Langerhans islets, lowering insulin levels, and raising HOMA-IR." (PMID 39055492, 2024). "Also, our study population was restricted to patients with type 2 diabetes who had baseline less than HbA1c of 8.5% and BMI ≥ 23 kg/m2 and not use insulin, glucagon-like peptide 1 agonist." (PMID 38693528, 2024). "However, this rise was significantly lower in insulin-resistant subjects, both with type 2 diabetes, and in obese non-diabetic subjects." (PMID 39125938, 2024). "NICE CGM reimbursement criteria for “adults (aged 18 years or over) with type 2 diabetes on multiple daily insulin injections” include but are not limited to recurrent hypoglycaemia or severe hypoglycaemia, impaired hypoglycaemia awareness, or if ≥ 8 self-measurements are required each day." (PMID 38709338, 2024). "Also of note, the finding of low diet quality among the insulin-taking group was not consistent with that of a previous study in Denmark where patients with Type 1 and Type 2 diabetes had higher adherence to dietary recommendations than the general population." (PMID 39458437, 2024). "However, nothing is known about the effects of IGFBP7 on insulin secretion in type 2 diabetes, or if IGFBP7 could be a therapeutic target to improve insulin secretion in clinical type 2 diabetes." (PMID 39280605, 2024). "He postulated that this syndrome plays a pivotal role in the development of type 2 diabetes mellitus (T2DM) and cardiovascular disease (CVD), primarily due to target tissue resistance to insulin action." (PMID 39502508, 2024). "In addition, fasting insulin levels have been shown to correlate positively with increasing body mass index (BMI) in large cohort studies, and fasting hyperglucagonaemia has been observed in obese insulin resistant people without type 2 diabetes." (PMID 38490484, 2024). "Whilst no medication was discontinued in the type 2 diabetes patients for the study duration, it is important to recognise that both metformin and statins use can result in a reduction or increase, respectively, in insulin resistance status." (PMID 38750012, 2024).
type 2 diabetes (continued). "Notably, changes in serum glucose were evident in young and old adult mice without changes in insulin levels, reminding us of the correlation between type II diabetes and metabolic syndrome in Alzheimer’s disease." (PMID 38410184, 2024). "The results of BEYOND seem to confute the dogma about the inevitability and eternity of basal-bolus regimen in type 2 diabetes by presenting the evidence around the feasibility and safety to switch either to a once-daily injection of a FRC or once-daily gliflozin pill added to basal insulin." (PMID 37787888, 2024). "Nine individuals with type 2 diabetes, six of whom had juvenile diabetes, one with adulthood-onset, and two without symptoms, received a dose of vegetable insulin (v-insulin) subcutaneously derived from Momordica charantia fruit that is similar to animal insulin or placebo." (PMID 39796448, 2024). "The aim of this retrospective study was to assess the success rate of transition from BBI to GLP-1RA therapy (with or without addition of basal insulin) in a cohort of obese patients with poorly controlled type 2 diabetes, in which long-term BBI therapy had failed." (PMID 38792590, 2024). "Type I diabetes mellitus (TIDM) results from autoimmune destruction of the insulin-producing β-cells in the islets of Langerhans in the pancreas, resulting in the production of little or no insulin and type II diabetes mellitus (TIIDM) is characterised by insulin resistance by cells." (PMID 38338467, 2024). "Moreover, SGLT-2i’ effectiveness in reducing MACE is particularly evident in patients managing type 2 diabetes with insulin, without heart failure, and those on steroids and tacrolimus." (PMID 39567483, 2024). "As a result of their insulin-independent mechanism of action, SGLT-2 inhibitors can be used for monotherapy and as a component of combination therapy with other antidiabetic agents with complementary modes of action to improve glycaemic control in patients with type 2 diabetes." (PMID 39063919, 2024). "The other reason could be that type 2 diabetes patients are treated by insulin when their blood glucose level is not controlled by oral anti-diabetics." (PMID 36952453, 2023). "While type 2 diabetes usually does not require insulin-based treatments, for patients affected with type 1 diabetes, as no cure currently exists, the only possible therapeutic approach consists of a lifelong exogenous insulin replacement therapy (with multiple daily injections." (PMID 37836872, 2023). "Clinical data were collected for 645/775 patients (mean age 64 ± 15(SD) years; 351 (54.4%) males from 40/43 general practices; 96.4% had type 2 diabetes; 6.5% were insulin treated, 54.3% non-insulin treated, 31.5% both insulin and non-insulin treated and 3.4% diet only." (PMID 36741969, 2023). "Besides insulin, IDE is able to cleave many substrates in vitro, including amyloid beta peptides, making this enzyme a candidate pathophysiological link between Alzheimer's disease (AD) and type 2 diabetes (T2D)." (PMID 37817156, 2023). "However, recent research addressing structured SMBG that includes education, SMBG profile, and feedback, indicates improved blood glucose levels in all persons with type 2 diabetes including those not treated with insulin." (PMID 37606977, 2023). "Moderately affected COVID-19 patients with type 2 diabetes could safely be treated with antihyperglycemic medications with or without insulin." (PMID 36701712, 2023). "Our study demonstrates that the insulin secretory response and consequently the glucose variations following oral or intravenous glucose tolerance tests after a 36 h fasting period differ among non-obese, obese and people with established type 2 diabetes." (PMID 36771218, 2023). "In addition, while neutrophils are not insulin responsive in the classical sense, a reduction in complex 1 activity has been shown in the neutrophils of patients with type 2 diabetes." (PMID 36326284, 2023).
type 2 diabetes (continued). "However, he also suggested that resistance to insulin-stimulated glucose uptake is present in more than 80% of individuals with impaired glucose tolerance or type 2 diabetes, and in about 25% of nonobese individuals with normal glucose tolerance." (PMID 36901984, 2023). "Blood alanine transaminase (ALT), insulin, and LDL cholesterol, elevated levels of which are associated with deteriorating health and type 2 diabetes, also did not change between week 0 and week 10 within the probiotic arm (n = 21), nor between arms (paired and unpaired t-test, respectively)." (PMID 36803658, 2023). "Therefore, we included 105 patients with type 2 diabetes who required insulin in the ICU and had at least 10 blood gas glucose values (No CGM group)." (PMID 36263915, 2023). "Type 2 diabetes mellitus (T2DM) is another proteinopathy with an alarming prevalence rate of 536 million worldwide, characterized by peripheral insulin resistance, high blood glucose levels and increased insulin secretion, which in time lead to a diminishment of β-cell functionality and number." (PMID 38027497, 2023). "On contrary, TNF-α neutralization in type 2 diabetes patients failed to affect insulin sensitivity." (PMID 37168278, 2023). "In people with type 2 diabetes, exendin 9-39 did not alter hepatic extraction of insulin." (PMID 37751301, 2023). "In type 2 diabetes, the body’s cells do not respond effectively to insulin." (PMID 37238305, 2023). "Specifically, MR showed that higher childhood BMI, corrected for genetic liability to adulthood BMI, has protective effects on insulin secretion and sensitivity traits, but that higher childhood BMI, corrected for genetic liability to adulthood BMI, was not protective for type 2 diabetes." (PMID 37280435, 2023). "In patients with type 2 diabetes insulin is used when the pills no longer work." (PMID 37377235, 2023). "Based on the negative role of FoxO-1 in insulin action, FoxO-1 inhibitors may be applicable as a new therapeutic approach to treat metabolic disorders, including type 2 diabetes." (PMID 36596838, 2023). "φb, integrated initial insulin and C-peptide responses in people with and without type 2 diabetes." (PMID 37751301, 2023). "However, this procedure is often challenging for specific groups of patients, including those suffering from type 2 diabetes mellitus (T2DM) and on insulin or intensive oral hypoglycemic therapy due to the increased risk of hypoglycemia after prolonged fasting." (PMID 37365577, 2023). "Thus, hyperinsulinemia in insulin- or insulin analog-treated patients with type 2 diabetes can be categorized as either immunity-induced or non-immunity-induced hyperinsulinemia (real hyperinsulinemia)." (PMID 37324170, 2023). "This study confirmed the increase in insulin-stimulated whole-body glucose disposal reported for HBO previously but further detected an early improvement in fasting glucose metabolism in the liver and lipolysis in WAT by employing stable isotope dilution technique in humans with type 2 diabetes." (PMID 36178534, 2023). "Thus, the lack of LEPTIN negatively affects insulin mediated glucose metabolism, further obstructing glucose regulation and contributing to type II diabetes." (PMID 37705071, 2023). "However, the underlying cellular mechanisms, specifically the initial effects on insulin signalling and mitochondrial capacity, have not yet been investigated, particularly in the context of type 2 diabetes." (PMID 36178534, 2023). "In NAFLD mice, butyrate restores intestinal barrier function by increasing ZO-1 expression and mitigates metabolic disorders and intestinal epithelial impairment in type 2 diabetic mice by promoting insulin secretion without compensatory hyperplasia in pancreatic β cells." (PMID 38201117, 2023). "Insulin, C-peptide and glucagon concentrations in subjects with and without type 2 diabetes." (PMID 37751301, 2023).
type 2 diabetes (continued). "In addition, a wide range of medications, such as insulin, GLP-RA, and SGLT2i, were used for glucose control in these studies; insulin pumps in patients with type 2 diabetes were not explored." (PMID 37685740, 2023). "The ability of insulin to stimulate glucose transport in muscle and fat cells is mediated by the regulated delivery of intracellular vesicles containing glucose transporter-4 (GLUT4) to the plasma membrane, a process known to be defective in disease such as Type 2 diabetes." (PMID 37520260, 2023). "Furthermore, the intermittent use of rtCGM in people with type 2 diabetes on oral anti-diabetic drugs, with or without basal insulin, is emerging as an effective strategy in lowering HbA1c in the short-term." (PMID 37676398, 2023). "The GK rat exhibits many features that make it an attractive model for Type II diabetes, including the fact that it is non-obese, non-insulin dependent, polygenic, and spontaneously develops impaired insulin secretion by 2 weeks with impaired fasting hyperglycemia by 4 weeks." (PMID 37034167, 2023). "In addition, in a study on 17 subjects with well-controlled type 2 diabetes patients who were taking glucose-lowering drugs, resveratrol treatment for 30 days failed to improve insulin sensitivity in peripheral tissues and the liver." (PMID 38027557, 2023). "In type-I diabetes, the body’s immune system attacks and destroys the cells in the pancreas that produce insulin, while in type-II diabetes, the body becomes resistant to the effects of insulin or does not produce enough insulin to regulate blood sugar levels properly." (PMID 37049866, 2023). "Therefore, long-term FMT treatment may enhance skeletal muscle insulin sensitivity via AMPK activation, thereby preventing the development of type 2 diabetes." (PMID 36915683, 2023). "Replacement of testosterone improved insulin sensitivity and reduced fat mass in hypogonadal men with type 2 diabetes mellitus (T2DM), but did not have any effects on endogenous glucose production or glucose disposal rates following medically induced short-term hypogonadism." (PMID 36860364, 2023). "The results from two studies examining the effects of 4–4.5 g spirulina supplementation from 6 to 12 weeks in people with overweight or obesity, or with type 2 diabetes, showed no changes in fasting blood glucose or insulin levels after spirulina supplementation." (PMID 36557218, 2022). "In this regard, a randomized cross-over clinical study on purslane seed consumption (10 g/day) with 240 ml low-fat yogurt revealed a slight decrease in FBS but no notable impact was observed on serum insulin levels or HOMA-IR score in 48 patients with type 2 diabetes for five weeks." (PMID 36474567, 2022). "Recent available research suggests that overall the IF regimens that incorporated TRE were well tolerable as a non-medicinal treatment option for patients with type 2 diabetes, and patients were able to reverse their need for insulin therapy during therapeutic IF/TRE protocols." (PMID 35053991, 2022). "Although the association between dietary BCAA and CVD risk among individuals with type 2 diabetes has not been reported, several studies have demonstrated the effect of dietary BCAA on metabolic biomarkers (e.g., TG, SBP, insulin, and HOMA-IR), obesity, type 2 diabetes, and CVD risk or mortality." (PMID 36313094, 2022). "Although GLP‐1 deficiency maybe unlikely to contribute to impaired insulin action in type 2 diabetes, low GLP‐1 levels are a potential risk factor in the development of type 2 diabetes." (PMID 34519026, 2022). "Prior decades of careful phenotyping and molecular characterization has led to description of several subphenotypes of what would have previously considered either type 1 diabetes (young onset, insulin sensitive and autoimmune) or type 2 diabetes (later onset, insulin resistant non-autoimmune)." (PMID 36090990, 2022).
type 2 diabetes (continued). "Interestingly, a similar observation was also reported in a similar type II diabetes model, where the authors confirmed blood glucose recovery was not a result of increased insulin production." (PMID 35665251, 2022). "First, we could not differentiate between type 1 and type 2 diabetes because there was no information on serum insulin, C-peptide, and pancreatic autoantibodies in the current KNHANES data." (PMID 36010223, 2022). "Finally, an overall insulin secretion pathway signature score was calculated for each of the low- and high-HbA1c (or non-diabetic and type 2 diabetes) samples and the score was plotted against FHL2 expression." (PMID 35802167, 2022). "In normal weight, good to moderate glucose balance, no insulin therapy, mild to moderate hypercholesterolemia, and normotriglyceridemia, in type 2 diabetics, campesterol and sitosterol concentrations were 7–9% in VLDL, 3–4% in IDL, 59–61% in LDL, and 27–30% in HDL." (PMID 35299760, 2022). "We induced metabolic disease through a combination of HFHS diet with an early single injection of low dose STZ, which resulted in a reproducible phenotype of metabolic disease featuring obesity and early signs of type II diabetes without the need for insulin treatment." (PMID 34849611, 2022). "Therefore, it seems that the findings of our investigation and the four previous studies support the notion that different chamomile varieties ameliorate type 2 diabetes without increasing insulin secretion or the secretory capacity of the pancreas." (PMID 36160451, 2022). "Thus, our study indicates in type 2 diabetes the absence of relevant effects of incretin hormones on insulin clearance." (PMID 35169165, 2022). "Interestingly, automated insulin delivery has been tested in patients with type 2 diabetes on artificial nutrition and admitted to in-hospital non-critical units." (PMID 35353250, 2022). "In conclusion, we reassessed the biomarkers to examine the function of pancreatic beta cells in type 2 diabetes and found that C‐CPI may serve as a convenient useful biomarker for not only the requirement current insulin treatment but also the requirement of insulin therapy for 4 years." (PMID 35229479, 2022). "The non-metformin group in our study mainly included patients treated with insulin, a second-line medication for type 2 diabetes patients in which hyperglycemia could not be controlled with metformin." (PMID 36139470, 2022). "Finally, none of the men with type 2 diabetes included were on insulin treatment, and, our study only included men, which limits the generalizability of the results to women and type 2 diabetes patients with a higher degree of beta-cell failure." (PMID 36387850, 2022). "For patients with type 2 diabetes mellitus (T2DM), the severity of CAC appears to be a stronger clinical prognostic indicator than conventional measures of disease severity, such as insulin use or glycemic control." (PMID 35757317, 2022). "Type 2 diabetes mellitus (T2DM) refers to a relative lack of insulin." (PMID 36437835, 2022). "Additionally, there is no systematic review dedicated exclusively to insulin management in type 2 diabetes during Ramadan." (PMID 35634376, 2022). "Additionally, unlike adults, treatment with metformin or insulin failed to prevent this β-cell decline in youth with prediabetes or type 2 diabetes." (PMID 36098974, 2022). "Simply treating type 2 diabetes with insulin may not be sufficient due to the insulin resistance of the cells, and this aspect of the condition needs to be addressed in the treatment." (PMID 35887304, 2022). "Type 2 diabetes is a non-autoimmune, multifactorial metabolic disorder characterized by chronic hyperglycemia resulting from impaired insulin secretion and altered action of insulin." (PMID 35227307, 2022).